EML5 (EMAP like 5)
Description:
May modify the assembly dynamics of microtubules, such that microtubules are slightly longer, but more dynamic.
Synonyms: EMAP-5; HuEMAP-2; EMAP-2; FAP16
Tractability: PROTAC: ubiquitination databases record sites on it.
Gene: Protein-coding gene on chromosome 14 (88,612,240 to 88,792,994, reverse strand). Ensembl gene ENSG00000165521.
Subcellular location: Cytoplasm, cytoskeleton
Gene Ontology:
Molecular function: microtubule binding
Cellular component: extracellular exosome; cilium; cytoskeleton
Genetic constraint (gnomAD): Loss-of-function variants: 97 observed, 203.41 expected, observed/expected ratio (o/e) 0.48, 90% interval 0.4 to 0.56. The upper end of that interval is the gene's LOEUF score, 0.56, which puts it in group 2 of 6, group 1 being the genes least tolerant of losing a copy. Missense variants: 1,894 observed, 2,300.7 expected, observed/expected ratio (o/e) 0.82, 90% interval 0.79 to 0.86. Synonymous variants: 736 observed, 769.72 expected, observed/expected ratio (o/e) 0.96, 90% interval 0.9 to 1.02.
Homologues: Orthologues: chimpanzee EML5 (99% identical), macaque EML5 (99% identical), dog EML5 (97% identical), rabbit EML5 (96% identical), rat Eml5 (96% identical), mouse Eml5 (96% identical), guinea pig EML5 (93% identical), tropical clawed frog eml5 (89% identical), zebrafish eml5 (85% identical). Paralogues in human: EML6 (74% identical), EML4 (15% identical), EML1 (14% identical), EML3 (14% identical), EML2 (12% identical), CFAP44 (12% identical), WDR90 (11% identical), CFAP251 (9% identical), CFAP52 (6% identical).
Diseases named in the same sentence as EML5 in open-access papers:
EML5 is named in the same sentence as 2 diseases in open-access papers, as found by Europe PMC text mining. Sharing a sentence is not in itself a finding about the gene and the disease. The quoted sentences say what the papers report.
breast carcinoma (1 paper, 2022). "Analysis of rare missense variants identified evidence of associations of TMEM161A, SIPA1L1, and ERCC2 with overall breast cancer, RNF175 and NCKAP1L with ER-positive disease, and SLC22A10, PHAX, SMARCA2, EML5, NTRK3, and MED23 with ER-negative disease." (PMID 35884425, 2022). "When missense variants were assessed, three further associations were observed for overall breast cancer (TMEM161A, SIPA1L1, ERCC2), and a further seven were observed for subtypes (RNF175, NCKAP1L, PHAX, SMARCA2, EML5, NTRK3, MED23)." (PMID 35884425, 2022). "As mentioned in the previous section, we observed modest evidence of a negative association with overall breast cancer risk for LoF variants in EML5, which is in contrast with the observed association of missense variants in this gene with ER-negative disease." (PMID 35884425, 2022). "A negative overall association with breast cancer risk was observed for EML5 (OR = 0.41 (CI 95% 0.18–0.94), p-value = 0.035)." (PMID 35884425, 2022). "The best putative candidates in this group were TMEM161A, ERCC2, and SIPA1L1 for overall breast cancer, RNF175 and NCKAP1L for ER-positive disease, and PHAX, SMARCA2, NTRK3, EML5, and MED23 for ER-negative disease." (PMID 35884425, 2022).
cancer (3 papers, 2022 to 2023). A tumor composed of atypical neoplastic, often pleomorphic cells that invade other tissues. "Confirmed by sequence analysis, this non-synonymous substitution affects an amino acid residue located within a WD40 domain repeat of the EML5 protein and corresponds to a human EML5 mutation associated with cancer (Wellcome Sanger Institute)." (PMID 35478957, 2022). "While assessing the relationship between SLC31A1 and these genes, we discovered that CYB561, URF4, and EML5 were significantly correlated with SLC31A1 expression in the preponderance of cancers." (PMID 37853210, 2023). "Future studies could investigate EML5 isoforms as potential cancer-testis antigens." (PMID 35478957, 2022).